RNU6-40P (RNA, U6 small nuclear 40, pseudogene)
Synonyms: RNU6-40
Gene: Small nuclear RNA gene on chromosome 1 (31,497,577 to 31,497,683, reverse strand). Ensembl gene ENSG00000206981.
Homologues: Orthologues: chimpanzee U6 (100% identical), guinea pig U6 (93% identical). Paralogues in human: RNU6-1 (96% identical), RNU6-2 (96% identical), RNU6-3P (96% identical), RNU6-4P (96% identical), RNU6-5P (96% identical), RNU6-6P (96% identical), RNU6-9 (96% identical), RNU6-12P (95% identical), RNU6-13P (95% identical), RNU6-17P (95% identical), RNU6-18P (95% identical), RNU6-25P (95% identical), and 1287 more.